TLR4 (toll like receptor 4)
Diseases named in the same sentence as TLR4 in open-access papers (continued):
Sharing a sentence is not in itself a finding about the gene and the disease.
Pancytopenia (1 paper, 2021). An abnormal reduction in numbers of all blood cell types (red blood cells, white blood cells, and platelets). "We demonstrate that T cells lacking TLR2, TLR4, or IL-6 successfully induced severe pancytopenia and BMF." (PMID 33711076, 2021).
panuveitis (1 paper, 2019). A disorder characterized by inflammation of the entire uvea which includes the iris, ciliary body, and choroid. "Endotoxin-induced uveitis (EIU) in mice mimics human panuveitis and is induced by lipopolysaccharide (LPS), a component of a gram-negative bacterial cell wall, which activates inflammatory Toll-like receptor 4 (TLR4) signaling." (PMID 31540271, 2019).
paroxysmal AF (1 paper, 2025). "Studies have reported elevated TLR4 expression in AF patients, with particularly high levels observed in those with persistent AF compared to paroxysmal AF, indicating a potential correlation between TLR4 and AF severity." (PMID 41357167, 2025).
parvovirus infection (1 paper, 2021). "Ferulic acid protected against porcine parvovirus infection-induced apoptosis by suppressing the NF-κB and TLR4." (PMID 34630083, 2021).
pelvic inflammatory disease (1 paper, 2010). Pelvic inflammatory disease (PID) is an acute or chronic inflammation in the pelvic cavity. "Intrauterine infusion of purified LPS caused pelvic inflammatory disease, with accumulation of granulocytes throughout the endometrium of WT but not Tlr4−/− mice." (PMID 20877575, 2010).
periodic paralysis (1 paper, 2017). "In PM patients, TLR4 expression was significantly increased compared with that of patients with periodic paralysis." (PMID 28446897, 2017).
Periventricular cysts (1 paper, 2013). "Intracerebral injection of LPS into the developing periventricular white matter of immature rodents results in the loss of oligodendrocytes, hypomyelination and formation of periventricular cysts through the action of TLR4." (PMID 23388509, 2013).
pharyngeal squamous cell carcinoma (1 paper, 2020). A squamous cell carcinoma that arises from the pharynx. "Taken together, these observations indicated that tilianin may exert cytotoxicity and immune surveillance against FaDu cells by acting on TLR4 and p65, thereby providing novel insights into the treatment of human pharyngeal squamous cell carcinoma." (PMID 32194422, 2020). "Considering the crucial role of TLR4 and p65 in tumor treatment, tilianin may be a potential drug for the treatment of pharyngeal squamous cell carcinoma." (PMID 32194422, 2020).
plague (1 paper, 2014). Plague is a severe bacterial infection caused by the gram-negative bacterium Yersinia pestis. "Nevertheless, our results suggest that overall, the antibody response to the plague F1-V vaccine did not depend on the presence of Tlr2 or Tlr4." (PMID 24995344, 2014).
platelet disorders (1 paper, 2014). "These primary data indicate a likely mechanism for thrombin-stimulated platelet aggregation and TLR4 expression and also provides a basis for further investigation of TLR4 modulation as a therapeutic strategy for coagulopathy and platelet disorders." (PMID 24489676, 2014).
polyneuropathy (1 paper, 2024). A disease or disorder affecting more than one nerve. "Although TLR4 plays a key role in models of mono and polyneuropathy there may be multiple cell types involved." (PMID 39696684, 2024).
postmenopausal osteoporosis (1 paper, 2024). Metabolic disorder associated with fractures of the femoral neck, vertebrae, and distal forearm. "8993C>T TLR4 polymorphisms involved in the etiology of postmenopausal osteoporosis." (PMID 38504994, 2024). "However, a large sample clinical study with 424 postmenopausal women (58 ± 6 years) in Poland demonstrated that 8993C>T TLR4 polymorphisms were involved in the etiology of postmenopausal osteoporosis." (PMID 38504994, 2024). "TLR4 is a key regulator of immune responses during chronic inflammation and postmenopausal osteoporosis in the postmenopausal females." (PMID 38504994, 2024).
pouchitis (1 paper, 2024). Acute inflammation in the intestinal mucosa of the continent ileal reservoir (or pouch) in patients who have undergone ileostomy and restorative proctocolectomy (proctocolectomy, restorative). "The expression of Toll-like receptors (TLRs) is also altered, with a decreased expression of TLR3 and increased expression of TLR5 in normal ileal pouch, and an upregulation of TLR2 expression in pouchitis and upregulation of TLR4 in both normal pouch and pouchitis." (PMID 38929596, 2024).
proliferative diabetic retinopathy (1 paper, 2015). Advanced retinopathy due to diabetes mellitus characterized by the formation of new vessels in the retina. "The expression of TLR4 in retinal vascular endothelial cells of patients with proliferative diabetic retinopathy and diabetic mice induced by streptozotocin was examined using immunofluorescence." (PMID 26468333, 2015).
promyelocytic leukemia (1 paper, 2022). "The missing link may be the expression of MD-2, a co-receptor necessary for TLR4 signaling, as it has been reported that JNK regulates MD-2 expression in the promyelocytic leukemia HL-60 cells." (PMID 36233127, 2022).
protozoal infection (1 paper, 2017). "The level of let-7i during protozoal infection with C. parvum infection was found reduced together with increase of TLR4 in biliary epithelial cells, contributing to cholangiocyte's defense responses." (PMID 28424428, 2017).
Pseudomonas infection (1 paper, 2017). Infections with bacteria of the genus pseudomonas. "PumA ensures efficient inhibition of innate immune responses by interacting with MyD88 and TIRAP, key adaptor proteins for IL‐1R and the main relevant TLRs in Pseudomonas infection (TLR4 and TLR5), as well as UBAP1 which regulates cytokine receptor pathways." (PMID 28483816, 2017).
pustular psoriasis (1 paper, 2019). "In addition, as seen with the marked improvement in our model with both TLR4 inhibition, and LCN2 blockade, these provide additional novel therapeutic targets in both chronic plaque and pustular psoriasis." (PMID 31024570, 2019).
Q fever (1 paper, 2025). A bacterial infection caused by Coxiella burnetii. "To explore this hypothesis, we have decided to investigate the role of TLR2 and TLR4 polymorphisms, as well as the potential influence of HLA alleles, in the development of acute Q fever." (PMID 40333225, 2025). "TLR2 (Arg753Gln) and TLR4 (Asp299Gly, Thr399Ile) polymorphisms, along with HLA-DRB1 alleles, were analyzed for 38 patients with acute Q fever, 38 matched controls, and 121 blood donors." (PMID 40333225, 2025). "Specifically, the aim was to identify whether certain TLR2 or TLR4 polymorphisms, or specific HLA-DRB1 alleles, act as risk or protective factors for the development of acute Q fever." (PMID 40333225, 2025).
rectum (1 paper, 2023). "Further, TLR4 expression by fibroblasts was associated with a high rate of recurrence (P = 0.0001) in left colon/rectum tumors." (PMID 35841426, 2023).
reflux oesophagitis (1 paper, 2021). "We showed that TLR2 and FXR were strongly upregulated, but TLR4 was unchanged during reflux oesophagitis." (PMID 33686512, 2021). "This study was the first to describe the expression of innate immunity receptors, TLR2 and TLR4, in the oesophageal squamous epithelium in a representative series of patients with and without reflux oesophagitis." (PMID 33686512, 2021). "In reflux oesophagitis, TLR2 expression significantly increased in superficial cells, but TLR4 expression did not change." (PMID 33686512, 2021).
renovascular hypertension (1 paper, 2019). High blood pressure secondary to renal artery stenosis. "This suggests that 8 weeks of aerobic ExT may decrease blood pressure in hypertensive rats by reducing the PICs activation through TLR4/MyD88/NF-κB signaling within the PVN, and thus delays the progression of 2K1C renovascular hypertension." (PMID 31708733, 2019). "Thus, to reveal the upstream signaling events that lead to decreased PICs production in the PVN following ExT, we tested the hypothesis that ExT can suppress TLR4/MyD88/NF-κB signaling in the PVN and thus attenuate two-kidney-one-clip (2K1C) renovascular hypertension." (PMID 31708733, 2019).
respiratory depression (1 paper, 2023). A decrease in ventilation secondary to impaired signals from the central nervous system. "Although TLR4 signaling activated by neonatal inflammation does not contribute to acute opioid-induced respiratory depression in neonates, significant cross-talk between opioid receptors and inflammatory signaling pathways exists, which may explain some similarities in responses." (PMID 37008014, 2023).
rhinosinusitis (1 paper, 2012). "In rhinosinusitis specimens, confocal analysis showed a clear TLR4/TLR9 co-localization in the cellular infiltrate of the sub-mucosa associated with marked damage of the epithelium." (PMID 22577387, 2012).
scoliosis (1 paper, 2024). A congenital or acquired spinal deformity characterized by lateral curvature of the spine. "Investigating the role of the TLR4/NF‐κB pathway in scoliosis could provide new insights into how resistin influences inflammation‐driven disease progression." (PMID 39664590, 2024).
Senile plaques (1 paper, 2024). Senile plaques are extracellular deposits of amyloid in the gray matter of the brain. "Additionally, other studies have demonstrated the increased expression of TLR2, TLR4, TLR5, TLR7, TLR9, and the co-receptor CD14 in microglial cells surrounding senile plaques in the brain tissues of patients with AD and AD mouse models." (PMID 38360834, 2024).
serous carcinomas (1 paper, 2014). "TLR4 expression was present in all ovarian epithelium (normal and neoplastic), whereas MyD88 was restricted to neoplastic cells, independent of tumour grade and associated with reduced progression-free and overall survival, in an immunohistological specific subset of serous carcinomas, p<0.05." (PMID 24977712, 2014). "While 73% (62/85) of malignant tumours were TLR4 positive (mixed subtypes), co-expression of MyD88 was observed in only 47% cases, which were all serous carcinomas." (PMID 24977712, 2014). "In contrast TLR4 in the absence of MyD88 was associated with non-malignant tissue, non-serous benign and borderline tumours, a subgroup of serous carcinomas and non-serous carcinomas (MyD88 negative EOC)." (PMID 24977712, 2014). "However in this study, TLR4/MyD88 co-expression showed a predilection for serous neoplasms in general, particularly borderline and malignant serous tumours, and was expressed in both high- and low-grade serous carcinomas." (PMID 24977712, 2014).
serous neoplasm (1 paper, 2014). "The expression of both TLR4 and MyD88 was most uniform and strongest in serous neoplasms, particularly borderline and malignant serous tumours." (PMID 24977712, 2014).
severe combined immunodeficiency (1 paper, 2020). Severe combined immunodeficiency (SCID) comprises a group of rare monogenic primary immunodeficiency disorders characterized by a lack of functional peripheral T lymphocytes resulting in early-onset severe respiratory infections and failure to thrive. "On the other hand, inflamed pulp tissues from mice with severe combined immunodeficiency (SCID) have shown a significantly increased expression of TLR‐2 and TLR‐4 (Mutoh, Watabe, Chieda, & Tani‐Ishii, 2009)." (PMID 32400961, 2020).
shigellosis (1 paper, 2012). Shigellosis is a bacterial infection leading to dysentery and is caused by Shigella, which are small, ubiquitous Gram-negative bacteria belonging to the enterobacteria family. "The pathogen-induced tissue injury is mediated, in part, by the TLR4-MD-2-LPS complex, and shigellosis provides a well-defined in vivo model for studying such damage." (PMID 22887873, 2012). "The TLR4-MD-2-LPS complex is involved in mediating this pathogen-induced tissue damage, and shigellosis is a well-defined disease model for its study." (PMID 22887873, 2012).
short bowel syndrome (1 paper, 2020). "Thus, HA or other TLR4 agonists may be useful in short bowel syndrome." (PMID 33552081, 2020).
sialadenitis (1 paper, 2024). Sialadenitis is an infection of the salivary glands. "A stronger TLR2 or TLR4 expression in IgG4-positive sialadenitis may indicate a tissue-related factor underlying this form of chronic sialadenitis." (PMID 39055281, 2024). "Taken together, these findings support the idea that innate immune responses mediated by TLR2 and/or TLR4 signalling play a role in the overexpression of IgG4-positive plasma cells in IgG4-positive sialadenitis, perhaps through mechanisms similar to those described in true IgG4-RD." (PMID 39055281, 2024). "A strong expression of TLR2 and TLR4 in IgG4-positive forms of sialadenitis may indicate a tissue-related factor as an antigen in this specific form of chronic sialadenitis." (PMID 39055281, 2024). "Thus, the stronger expression patterns of TLR2 and TLR4 we observed in the IgG4-positive group may indicate an aberrant role of TLR-mediated inflammatory responses in IgG4-overexpressing sialadenitis." (PMID 39055281, 2024).
skin infection (1 paper, 2022). An inflammatory process affecting the skin, caused by bacteria, viruses, parasites, or fungi. "By using computational methods: pharmacophore modeling and molecular docking, we identified a set of 46 potential modulators of TLR4, which were screened in several tests systems of increasing complexity, including immune responsive 3D-skin infection models." (PMID 35208698, 2022). "This study is in line with our finding using the immune-responsive 3D-skin infection model and co-culture test systems combining primary immune cells with fibroblasts, further supporting a prominent role for TLR4 and its co-receptors in epithelial defense mechanisms." (PMID 35208698, 2022).
spondylarthropathy (1 paper, 2010). "In addition, De Rijcke and colleagues showed that anti-TNF treatment in spondylarthropathy results in a reduced expression of TLR2 and TLR4." (PMID 21179534, 2010).
squamous cell carcinoma of the skin (1 paper, 2017). "A better understanding of the regulatory role for TLR4 will be the basis for a later use in a therapeutic setting to impair keratinocyte proliferation such as in squamous cell carcinoma of the skin and to induce keratinocyte proliferation such as in wound healing." (PMID 28982115, 2017).
staphylococcal infection (1 paper, 2018). An infection caused by Staphylococcus. "However, TLR4, which has been identified as the dominant inflammatory receptor for HMGB1, had no impact or very limited impact on the host response during staphylococcal infections." (PMID 29922279, 2018).
stress-related disorder (1 paper, 2014). Stress-related disorders are mental health disorders that are a result of an atypical response to both short and long-term anxiety due to physical, mental, or emotional stress. "The current review thus posits that TLR4, being central to the immune to brain, and immune to neuroendocrine communication, underlies the neuroimmune signaling events observed in the pathophysiology of stress-related disorders including MDD, across systemic and cellular levels." (PMID 25324715, 2014). "This suggests that TLR4 activity during developmentally sensitive periods may shape the HPA system, priming the system toward hyper-reactivity, and may even be changing individual predisposition toward stress-related disorders." (PMID 25324715, 2014).
structural epilepsy (1 paper, 2020). A type of epilepsy that is conceptualized as having a distinct structural brain abnormality that has been demonstrated to be associated with a substantially increased risk of epilepsy in appropriately designed studies. "Comparison between groups indicated an induction of TLR4 expression in the hippocampal CA3 region of dogs with structural epilepsy, whereas TLR4 expression proved to be in the control range in dogs with idiopathic epilepsy." (PMID 31959173, 2020). "Analysis of components of the TLR4-signaling cascade revealed different expression patterns in canine patients with idiopathic and structural epilepsy." (PMID 31959173, 2020). "Higher TLR4 expression rates might thus constitute a long-term consequence of an initial epileptogenic insult resulting in development of structural epilepsy in canine patients." (PMID 31959173, 2020). "Increased expression levels might result in excessive inflammatory signaling in dogs with structural epilepsy taking into account that TLR4 activation results in enhanced generation and release of pro-inflammatory cytokines including interleukin-1β and tumor-necrosis factor α." (PMID 31959173, 2020).
Takayasu arteritis (1 paper, 2023). A rare inflammatory large-vessel vasculitis primarily affecting the aorta and its major branches, but also other large vessels, causing stenosis, occlusion, or aneurysm. "Compared with the healthy control group, the expression of TLR4 in Takayasu arteritis patients has an upward trend." (PMID 37217870, 2023). "The activation of TLR-4 may play an important role in the pathogenesis of Takayasu arteritis." (PMID 37217870, 2023).
testis cancer (1 paper, 2022). "Except that the high expression of TLR4 was associated with the poor prognosis of testis cancer, the effects of other genes on the survival of patients with different tumors were all consistent with that of our study." (PMID 35911966, 2022).
thoracic aortic aneurysm (1 paper, 2022). An aneurysm formed in the wall of the proximal portion of the descending aorta proceeding from the arch of the aorta. "Previous research has suggested that TLR4 may have a role in the development of thoracic aortic aneurysms (TAA), whereas fewer reports have investigated the role of TLR4 in TAAD." (PMID 37205167, 2022).
tongue cancer (1 paper, 2024). A malignant neoplasm affecting the tongue. "OSCC cell lines with positive TLR4 expression, OSC20, OSC19, and SAS, which originated from tongue cancer, and OSCC cells with negative TLR4 expression, Ca9-22, which were from gingival carcinoma, were examined." (PMID 38254832, 2024).
tracheobronchitis (1 paper, 2023). Inflammation of the tracheobronchial tree. "Results showed that organic acids could treat acute tracheobronchitis by regulating the TLR4/NF-κB signaling pathway, indicating that organic acids have certain anti-inflammatory effects." (PMID 37999247, 2023).
trachoma (1 paper, 2016). "The results showed an association between TLR4 and MICA polymorphisms and trachoma disease severity, as well as with protection." (PMID 27559544, 2016). "Our results indicate that MICA-A9 and TLR4 Asp299Gly heterozygosity may confer a selective advantage in Tanzanian populations where Trachoma is endemic." (PMID 27559544, 2016).
Tremor (1 paper, 2018). An unintentional, oscillating to-and-fro muscle movement about a joint axis. "PD patients with the tremor‐dominant subtype mainly had the clinical manifestation of limb tremor without obvious muscle rigidity and had serum HMGB1 and TLR4 levels of 5.08 ± 0.96 and 2.52 ± 0.72, respectively." (PMID 29670828, 2018).
Trichiasis (1 paper, 2016). Inversion and rubbing of the eyelashes against the globe of the eye. "The association of TLR4 Asp299Gly and MICA exon 5 microsatellites with inflammatory trachoma (TI) and trichiasis (TI) were examined." (PMID 27559544, 2016).
tubulointerstitial nephritis (1 paper, 2013). "Instead, activation of TLR2 and TLR4 by LPS on renal epithelial cells is thought to cause tubulointerstitial nephritis." (PMID 23809518, 2013).
tularemia (1 paper, 2012). Tularemia is an infection caused by the bacterium Francisella tularensis. "However, work by others indicates TLR4 stimulation alone is an insufficient method to protect against experimental tularemia, particularly, when administered after infection." (PMID 22438809, 2012).
urinary obstruction (1 paper, 2014). "Hence, TLR4 activation has been shown to favor kidney fibrosis in the mouse model of unilateral urinary obstruction." (PMID 24498450, 2014).